ALB (albumin)
Diseases named in the same sentence as ALB in open-access papers (continued):
Sharing a sentence is not in itself a finding about the gene and the disease.
malnutrition (continued). "The blood urea nitrogen to serum albumin ratio is a novel and easily accessible prognostic biomarker that integrates indicators of malnutrition, inflammation, protein metabolism, and renal function." (PMID 40806817, 2025). "Malnutrition was observed in 72% (75/104) of the participants, with affected children exhibiting significantly lower body weight and serum albumin levels." (PMID 40981163, 2025). "Patients with loss of appetite and weakened digestion and absorption are prone to malnutrition, leading to decreased albumin synthesis." (PMID 40104144, 2025). "Malnutrition markers such as low albumin, low cholesterol, low haemoglobin and limb circumference were associated with frailty." (PMID 40863223, 2025). "Albumin, the most abundant protein in human serum, has long been used as an indicator of malnutrition in clinically stable patients." (PMID 39940424, 2025). "Serum albumin is an essential indicator of malnutrition in patients and plays a vital role in immune regulation, possessing anti-inflammatory and antioxidant properties." (PMID 40765739, 2025). "Model 1 was adjusted for age, sex, and BMI; Model 2 was adjusted for Model 1 and presence of ADHF and dementia; and Model 3 was adjusted for Model 2 and inflammation (CRP levels), renal dysfunction (creatinine levels), and malnutrition (albumin levels)." (PMID 40573090, 2025). "And it is necessary to conduct a nutritional assessment for patients with normal postoperative albumin levels to distinguish patients with malnutrition." (PMID 40432957, 2025). "Within this context, albumin functions as a summary signal of the malnutrition-inflammation complex and the broader protein-energy wasting construct - both recognized drivers of adverse outcomes in HD." (PMID 41552166, 2025). "Albumin has 2.5–3 d half-life in rats, allowing for short-term assessment of hepatotoxicity, renal toxicity, and malnutrition." (PMID 40231165, 2025). "A low CALLY score (meaning high CRP, low albumin, and low lymphocytes) signifies a state of inflammation with malnutrition and immunosuppression." (PMID 41009701, 2025). "In advanced CKM participants, low ALB levels typically reflect the combined effects of malnutrition and chronic inflammation, both of which have an essential function in the progression of CVDs and renal dysfunction." (PMID 40740647, 2025). "NAR, as a marker representing the ratio of neutrophils to albumin, indicates systemic inflammation and malnutrition and, as such, is determined in many malignant and autoimmune diseases." (PMID 41230322, 2025). "Some of the most common variables used to diagnose malnutrition are albumin, mid-arm muscle circumference, BMI, cholinesterase, hemoglobin, neutrophil-to-lymphocyte ratio, and the total number of lymphocytes." (PMID 40538582, 2025). "Previous research has indicated that serum albumin levels are typically lower in cirrhotic patients with malnutrition." (PMID 40805938, 2025). "While increased CRP indicates the severity of the inflammatory response, low albumin levels are generally considered a sign of malnutrition and catabolic processes." (PMID 40005437, 2025). "Historically, serum visceral proteins, including prealbumin and albumin, have been used to diagnose malnutrition." (PMID 40989906, 2025). "First, malnutrition weakens the body’s immune defense, with low serum albumin levels impairing the production and function of immune cells, particularly T-lymphocytes." (PMID 40577338, 2025). "This suggests HALP captures broader aspects of disease progression, combining markers of malnutrition (albumin, hemoglobin) and inflammation (lymphocyte and platelet counts)." (PMID 41473656, 2025). "It is said that cancer patients with various tumor types exhibit a typical acute phase protein response, with increased CRP and decreased albumin, leading to high inflammation and malnutrition." (PMID 40647430, 2025).
malnutrition (continued). "Decreased eGFR was correlated with increased age, higher UACR, high uric acid, and the presence of malnutrition indicators (low serum albumin, low HDL-cholesterol, high triglycerides, and low MNA score)." (PMID 40566551, 2025). "When elevated GDF15 was combined with low albumin (< 36.15 g/L), the model’s predictive accuracy for malnutrition significantly improved (AUC = 0.935), outperforming single indicators." (PMID 40697555, 2025). "Malnutrition, characterized by an inadequate intake of essential nutrients, leads to a decrease in serum albumin levels and lymphocyte counts." (PMID 40507116, 2025). "Biochemical and hematological venous blood parameters, such as albumin, are commonly used to diagnose malnutrition in patients." (PMID 40094974, 2025). "Low PNI levels (HR: 0.24, P = .005), i.e., low albumin levels, indicate malnutrition, which is an unfavorable prognosis in cancer." (PMID 40241388, 2025). "Serum albumin assessment has prognostic value comparable to both simple and multidimensional malnutrition tools in CHF." (PMID 41007652, 2025). "Generally, in patients with cancer, albumin levels tend to drop more significantly during the middle and late stages of the disease, leading to hypoalbuminemia, which is indicative of malnutrition." (PMID 40650392, 2025). "Our findings support the validity of this explanation: patients in the L/H group had significantly lower albumin levels and total cholesterol, indicative of malnutrition." (PMID 41517492, 2025). "Since hypoalbuminemia is frequently observed in clinical scenarios such as chronic liver disease, malnutrition, and severe inflammation, accurate model selection under abnormal albumin levels is critical to avoid dosing errors and ensure therapeutic efficacy." (PMID 40732280, 2025). "In hematological and gastrointestinal malignancies, elevated C-reactive protein/albumin (CRP/ALB) ratios reflect progressive systemic inflammation and malnutrition, which are strongly associated with shortened overall survival." (PMID 40563367, 2025). "Lastly, albumin levels reflect the individual’s nutritional status and are indicative of malnutrition." (PMID 40740873, 2025). "A study involving 60 cardiac transplant recipients, evaluated at least five years post-transplant, demonstrated that serum albumin was a more reliable predictor of malnutrition compared to body mass index (BMI) and the SGA." (PMID 40161084, 2025). "Specifically, they had lower levels of nutritional indices, including serum albumin, GNRI, PhA, and MNA-SF®, further reinforcing the well-established association between sarcopenia and malnutrition." (PMID 41479669, 2025). "In turn, the inflammatory response can inhibit albumin synthesis, thereby exacerbating malnutrition and perpetuating a vicious cycle that accelerates disease progression." (PMID 40373393, 2025). "NLR and PLR are mainly related to inflammation, while ALB in the AAPR component is associated with both inflammation and malnutrition." (PMID 39941572, 2025). "The inflammation-induced hepatic acute-phase response prioritizes the synthesis of inflammatory proteins such as hsCRP, while inhibiting the production of nutrition-related proteins like albumin and prealbumin, thereby exacerbating malnutrition." (PMID 40431471, 2025). "Other indices like the Prognostic Nutritional Index (PNI), based on lymphocyte count and serum albumin levels, and the Geriatric Nutritional Risk Index (GNRI), which uses albumin and body weight, also serve as reliable indicators of malnutrition." (PMID 40777566, 2025). "In laboratory data, the moderate and severe malnutrition group exhibited lower levels of lymphocytes, total cholesterol (TC), albumin, and hemoglobin." (PMID 40697546, 2025). "Higher months on dialysis (Exp(B) = 1.02), unmet calorie intake (Exp(B) = 4.3), needing help in daily activities (Exp(B) = 0.238), and low albumin level (Exp(B) = 0.048) were the independent predictors of malnutrition." (PMID 39854402, 2025).
malnutrition (continued). "HCC patients often experience malnutrition due to factors such as reduced appetite and impaired nutrient absorption, which can lead to sarcopenia, myosteatosis, and decreased serum albumin levels." (PMID 40308633, 2025). "Low albumin thus signals malnutrition and an impaired host response, conditions that promote tumor progression and bone marrow infiltration." (PMID 41156248, 2025). "Conversely, excessive inflammation suppresses albumin synthesis, perpetuating malnutrition and creating a self-reinforcing cycle of adverse outcomes." (PMID 40777171, 2025). "Similar to previous reports, our study also found lower levels of albumin and TC, which are known indicators of malnutrition, in the deceased patient group of our study cohort." (PMID 39673344, 2025). "Low hemoglobin and albumin levels reflect anemia and malnutrition, while decreased lymphocyte and elevated platelet counts indicate immune dysregulation and systemic inflammation." (PMID 41235300, 2025). "Research has shown that alcohol consumption is associated with conditions such as low body weight and low serum albumin, both of which are signs of malnutrition." (PMID 40920784, 2025). "Albumin, prealbumin, and transferrin are strongly influenced by inflammation, fluid shifts, and disease severity, which reduces their specificity for malnutrition." (PMID 41515193, 2025). "Both malnutrition and inflammation can negatively affect albumin synthesis, resulting in reduced serum albumin levels." (PMID 40283046, 2025). "This is a deviation from the explicit recommendation by ESPEN against using visceral proteins like albumin for diagnosing malnutrition." (PMID 41323996, 2025). "Lower albumin levels in cases (p<0.001) further underscore the systemic effects of multiple myeloma, including chronic inflammation, malnutrition, and hepatic dysfunction." (PMID 40369504, 2025). "It is important to note that this difference cannot be solely explained by malnutrition, as most of our study participants had only mild anemia and normal serum albumin levels." (PMID 40197488, 2025). "Further analysis revealed that 2 of these 4 patients were in T4 stage, while the other 2 had baseline malnutrition with albumin levels < 30 g/L." (PMID 40760130, 2025). "Hypoalbuminemia (albumin <3.5 g/dl) in severe malnutrition impairs antioxidant defenses and nitric oxide bioavailability, exacerbating myocardial ischemia." (PMID 40777566, 2025). "Serum albumin level and body mass index are generally used as indicators of malnutrition, with recent reports showing that both are correlated with postoperative mortality." (PMID 40225113, 2025). "A meta-analysis conducted to assess malnutrition found that albumin and TC were significantly lower in both acute and chronic malnutrition patients." (PMID 39673344, 2025). "According to transferrin levels, malnutrition was demonstrated in 49% of subjects, according to albumin levels in 71.8% of subjects, and according to prealbumin levels, 76.5% of subjects were malnourished." (PMID 40612307, 2025). "It is the most abundant circulating protein found in plasma and can be susceptible to many factors influencing its levels, including inflammation and malnutrition, both of which can lower the concentration of albumin by decreasing the rate of synthesis." (PMID 40964588, 2025). "Clinically, decreased ALB concentrations are often related to malnutrition, inflammatory responses, and organ dysfunction." (PMID 40740647, 2025). "Inflammation and malnutrition reduce albumin levels by impairing synthesis and accelerating catabolism." (PMID 41586234, 2025). "Existing literature confirms that both malnutrition and inflammation contribute to decreased serum albumin levels." (PMID 40585729, 2025). "The following independent risk factors for post-hepatectomy OS in patients with HCC were identified: AFP ≥ 400 ng/mL; Malnutrition; serum albumin <35 g/L; maximum tumor diameter >5 cm; tumor and number ≥3." (PMID 40642170, 2025).
malnutrition (continued). "Multivariate analysis identified number of daily food types, cereal intake, high-quality protein intake, body mass index, serum albumin, and pre-albumin as malnutrition predictors (all P < 0.05)." (PMID 41220716, 2025). "Decreased albumin synthesis, increased catabolism, and exacerbated inflammation can lead to malnutrition." (PMID 40860683, 2025). "While BMI, hemoglobin, and total cholesterol were identified as reliable markers of malnutrition in older adults, albumin and prealbumin were less predictive in acute illnesses contexts, reflecting inflammation rather than nutritional status." (PMID 39940424, 2025). "Low serum albumin, a marker of malnutrition and systemic inflammation, likely reflects insufficient dietary protein intake, which is essential for muscle maintenance." (PMID 40915183, 2025). "Serum albumin levels are often decreased in HF patients due to factors such as hemodilution from fluid overload, malnutrition, and impaired hepatic synthesis." (PMID 41210328, 2025). "Multivariate Cox regression analysis identified the following independent risk factors for OS in patients with HCC undergoing hepatectomy: AFP ≥ 400 ng/mL; Malnutrition; serum albumin <35 g/L; maximum tumor diameter >5 cm; and tumor number ≥3." (PMID 40642170, 2025). "Preoperative malnutrition was defined as hypoalbuminemia with a serum albumin level of <35 g/L before surgery or a BMI of <18.5 kg/m2 within 30 days before surgery." (PMID 40225113, 2025). "Chronic diseases, malnutrition, and frailty alter both baseline levels (for example, renal disease elevates creatinine, hepatic dysfunction reduces albumin) and the kinetic behavior of markers during illness." (PMID 41357512, 2025). "Regular use of multidimensional tools (SGA, SNAQ, albumin) should be employed to enhance the early detection and management of malnutrition in patients with end-stage kidney disease (ESKD)." (PMID 41159942, 2025). "The CRP/Alb ratio captures the bidirectional interplay between these two domains: systemic inflammation drives protein catabolism and reduces albumin synthesis, while malnutrition impairs immune competence, fueling inflammation." (PMID 40573094, 2025). "Elderly patients with fractures are often accompanied by malnutrition, which leads to decreased serum albumin levels and decreased lymphocyte counts." (PMID 40860480, 2025). "Serum albumin level as a biomarker for inflammation and malnutrition has been extensively studied in cancer patients, with recent focus into specific oncologic populations such as those with spinal metastases." (PMID 40103850, 2025). "It is believed that, in comparison to low albumin, lymphopenia can be accepted as an indicator of malnutrition that is unaffected by elevated CRP." (PMID 40507738, 2025). "On the other hand, low albumin levels generally indicate chronic illness, malnutrition, or impaired liver function." (PMID 40416810, 2025). "Albumin is produced by the liver, and low albumin levels in the blood can be a sign of malnutrition and dysfunction in liver synthesis." (PMID 40334215, 2025). "A decrease in albumin levels often indicates malnutrition and impaired immune function, which are closely related to cancer onset, progression, and prognosis." (PMID 40716028, 2025). "The association of time‐varying hypoalbuminemia with total and cardiovascular mortality was reported to differ from that of basal fixed single measurements of serum albumin or other markers of malnutrition or inflammation." (PMID 40300783, 2025). "The association between GNRI and osteoporosis can be explained by utilizing two important markers of malnutrition in the tool, namely, albumin and BMI." (PMID 40290237, 2025). "For malnutrition, parameters such as albumin, body weight, hemoglobin, and calcium levels were measured." (PMID 40760640, 2025).
malnutrition (continued). "First, malnutrition, partially reflected by serum albumin and cholesterol levels, can impair overall physiological reserve and reduce tolerance to aggressive treatments, thereby worsening survival outcomes." (PMID 41154397, 2025). "At baseline, patients in group C had better malnutrition-inflammation scores, calf circumference, handgrip strength, Ishii scores, prealbumin, and albumin than the other two groups." (PMID 41414650, 2025). "Serum ALB and GLB levels are part of routine biochemical tests, and the albumin to globulin ratio (AGR) serves as a biomarker of malnutrition and inflammation, reflecting the prognosis of heart failure patients." (PMID 40980171, 2025). "Malnutrition leads to insufficient albumin synthesis, and the brain requires continuous adequate nutrition and energy supply to maintain normal function." (PMID 41346383, 2025). "Key markers include serum albumin and prealbumin, which reflect protein status, with low levels suggesting malnutrition." (PMID 39940424, 2025). "By considering both lactate elevation, which reflects hypoxia and metabolic disturbances, and albumin reduction, which signals immune suppression and malnutrition, LAR offers a more comprehensive assessment of prognosis." (PMID 40735448, 2025). "Hypoalbuminemia, defined as a serum albumin concentration of less than 3.5 g/dL, is often considered a standard indicator of malnutrition." (PMID 40094974, 2025). "Low PNI indicates malnutrition, characterized by low albumin, and/or impairment of adaptive immunity, marked by lymphopenia, and is associated with more severe manifestations and poorer anti-TB treatment outcome." (PMID 40191188, 2025). "Hypoalbuminemia directly reflects a patient’s malnutrition status; albumin is crucial for maintaining colloid osmotic pressure and supporting tissue repair." (PMID 40469280, 2025). "Serum albumin serves as a comprehensive prognostic marker in the dialysis population, reflecting the combined impact of malnutrition, inflammation, and vascular pathology." (PMID 41283273, 2025). "Decreased serum cholesterol and albumin levels, along with reduced lymphocyte counts, are indicative of malnutrition." (PMID 41011049, 2025). "This study aimed to assess the malnutrition and sarcopenia scale in patients with frailty syndrome and the viability of evaluating the concentrations of the following potential biomarkers: albumin, total protein, and fibrinogen." (PMID 40944175, 2025). "Decreased albumin levels are a marker of malnutrition, which negatively affects the body’s recovery capacity, prolongs recovery time, and increases the risk of complications." (PMID 40077630, 2025). "A low BMI, low serum albumin, and a high ECOG Performance Status generally reflect a state of malnutrition and are associated with a deterioration of the patient’s overall condition." (PMID 40166057, 2025). "In the present study, we found a high prevalence (22.81%) of GLIM-defined malnutrition among patients with normal preoperative serum albumin." (PMID 40432957, 2025). "Hypoalbuminemia, a condition characterized by low serum albumin levels, not only indicates malnutrition but also reflects a sustained systemic inflammatory response, which can compromise anti-tumor immunity." (PMID 40741001, 2025). "Patients with NBD are prone to malnutrition, leading to decreased levels of total protein, albumin, and hemoglobin, which can exacerbate their condition and hinder recovery." (PMID 39975673, 2025). "According to the NPS scoring system, high NPS levels most likely presented underlying low albumin, low total cholesterol, low LMR, and high NLR, suggesting malnutrition and high inflammation status." (PMID 40568584, 2025). "A preoperative albumin level below 35 g/L is considered malnutrition and below 30 g/L is identified as hypoalbuminaemia." (PMID 40020120, 2025). "Serum albumin is a simple and valuable marker that can reflect malnutrition and cachexia in cancer patients." (PMID 40441260, 2025).